CDK1 (cyclin dependent kinase 1)
Diseases named in the same sentence as CDK1 in open-access papers (continued):
Sharing a sentence is not in itself a finding about the gene and the disease.
breast cancer (continued). "Remarkably, previous studies have revealed that the upregulated expressions of CDK1 and CCNB1 are correlated with the worse OS in the basal subtype breast cancer, while CDC20, CCNB1, and CDK1 could act as diagnostic and prognostic markers in breast cancer." (PMID 34646403, 2021). "All these implied that RBM7 could significantly affect the expression of CDK1 in breast cancer." (PMID 33145401, 2020). "More recently, GR activation has been observed in breast cancer metastases and was associated with a GR activation signature which included genes such as MELK, CDK1, and particularly the ROR1 kinase, which may mediate resistance to chemotherapeutic agents and increase colonization." (PMID 31675993, 2019). "In addition, HSP inhibition downregulated CDK1 expression in human breast cancer cells." (PMID 29069815, 2017). "Moreover, the CDK1 gene silencing with the application of RNAi was indicated as a novel potential tool for the therapy of malignant pleural mesothelioma, epithelial ovarian cancer, and breast cancer." (PMID 26912061, 2016). "Therefore, the direct targeting of CDK2 and CDK1 may be a useful therapeutic approach, particularly in anti-estrogen-resistant breast cancers (AERBC), where p27Kip1 levels are reduced." (PMID 20010939, 2010). "The results consistently demonstrated that NAT10 expression in breast cancer tissues positively correlated with CD2BP2‐DT and CDK1 levels, suggesting that NAT10 acts as an upstream regulator of the CD2BP2‐DT/CDK1 signaling axis." (PMID 39976088, 2025). "Our study demonstrated that NFIX plays a critical role in CDK1-regulated cell cycle transitions and determined that NFIX inhibits cell proliferation in breast cancer." (PMID 40000619, 2025). "Targeting CDK1, CDC25A, and PLK1 offers a promising therapeutic strategy in breast cancer due to their pivotal roles in cell cycle regulation." (PMID 40081286, 2025). "CDK1, CDC25A, and PLK1 were upregulated in breast cancer compared to normal tissues, based on BRCA data analysis." (PMID 40081286, 2025). "Kenpaullone inhibits KLF4 by suppressing CDK1/cyclin B and GSK-3β, reducing proliferation and migration of breast cancer cells in canine mammary cancer and inducing cancer cell death, although its effects in humans require further investigation." (PMID 39995670, 2025). "The CDK1/cyclinD6/4 and PI3K/AKT/mTOR pathways have become a desirable target for the treatment of many cancers, with resistant breast cancer being one of them, as tumorigenesis is largely dependent on uncontrolled cell cycle progression." (PMID 41348684, 2025). "Rescue experiments demonstrated that the inhibitory effect of stable CD2BP2‐DT knockdown on CDK1 expression was reversed by YBX1 overexpression in breast cancer, while the promoting effect of CD2BP2‐DT overexpression on CDK1 was inhibited by YBX1 knockdown." (PMID 39976088, 2025). "To further explore the properties of PAB-CDK1 interaction, we compared the effects of the CDK1 inhibitor Ro-3306 with those of PAB on canine mammary tumor cells." (PMID 41142571, 2025). "More importantly, CD2BP2‐DT enhances the stability of CDK1 mRNA by mediating YBX1 phase separation, thereby promoting the proliferation of breast cancer cells." (PMID 39976088, 2025). "The bioinformatics analysis identified CDK1, CDC25A, and PLK1 as pivotal genes regulating cell cycle progression and breast cancer tumorigenesis." (PMID 40081286, 2025). "CDC25B dephosphorylates and activates Cyclin-dependent Kinase 1/Cyclin B (CDK1/Cyclin B), which have been shown to be overexpressed in breast cancer and promote cell cycle progression." (PMID 40454580, 2025). "The multivariate logistics regression analysis was applied to evaluate the performance of the panel of 3 genes (CDK1,CDC25A and PLK1) as biomarkers for breast cancer prediction." (PMID 40081286, 2025).
breast cancer (continued). "From a mechanistic standpoint, CDK1 knockdown reduced AKT phosphorylation and downregulated Cyclin D1, A, and E1, leading to suppressed breast cancer cell proliferation." (PMID 41278293, 2025). "In the present study, we further analyzed the correlation between NAT10, CD2BP2‐DT, and CDK1 using bioinformatic databases and IHC on TMA in breast cancer." (PMID 39976088, 2025). "Several researchers had revealed that CDK1 inhibition induces MYC-dependent apoptosis through a synthetic lethal interaction between CDK1 and MYC in lymphomas, hepatoblastomas, and especially breast cancers." (PMID 40040723, 2025). "Targeting multiple genes, such as CDK1, CDC25A, and PLK1, effectively induces cell cycle arrest, offering a promising therapeutic strategy for breast cancer." (PMID 40081286, 2025). "Mechanistically, CDK1 knockdown reduced AKT phosphorylation and downregulated Cyclin D1, A, and E1, leading to suppressed proliferation of breast cancer cells." (PMID 41278293, 2025). "Dinaciclib, a drug that targets CDK1, CDK2, CDK5, and CDK9, has demonstrated efficacy in the treatment of breast cancer by reducing the expression of stem cell markers and decreasing cancer cell viability." (PMID 40004024, 2025). "Based on various bioinformatics, in silico docking and in vitro MCF7 cell line study reveals that the C. urens fruit extract targets the genes of cell cycle i.e. CDK1,CDC25A, and PLK1 in breast cancer." (PMID 40081286, 2025). "Cyclin-dependent kinase 1 (CDK1) plays a crucial role in regulating the cell cycle, yet its clinical relevance and molecular mechanisms in breast cancer remain insufficiently characterized." (PMID 41278293, 2025). "Functional studies revealed that PLCH1 was highly expressed in breast cancer cell lines, and PLCH1 knockdown significantly inhibited cell proliferation, induced cell cycle arrest, and reduced cyclin-dependent kinase 1 (CDK1) expression in BT-474 cells." (PMID 40519297, 2025). "Episesamin, a major phytoconstituent of C. urens, was found to target CDK1, CDC25A, and PLK1-key cell cycle regulators in breast cancer." (PMID 40081286, 2025). "Genes such as APP, CDK1, CDK2, and ESR1 were the most frequently observed in this list and have been previously extensively characterized in breast cancer." (PMID 38378612, 2024). "Interestingly, Bcl-2 has been reported to localize to the nucleus in various cancer types including breast cancer, endometrial carcinoma, squamous cell carcinoma, and astrocytoma, where it appears to take part in a multiprotein complex comprising CDK1, PP1, and nucleolin." (PMID 38228372, 2024). "In lung cancer, CDK1 drives SOX2 to maintain tumor cell stemness 34, and similar conclusions have been made in glioma and breast cancer 35,36." (PMID 38164286, 2024). "In breast cancer, KIAA1429 was shown to upregulate the expression of CDK1, thereby promoting the proliferation of breast cancer cells." (PMID 38164289, 2024). "It was seen through different databases that HMMR was highly upregulated in various malignancies, including breast cancer, and HMMR has a correlation with AURKA, TPX2, and CDK1, which are also involved in the upregulation of mTOR signaling pathways." (PMID 38576486, 2024). "We identified several DEGs involved in the cell cycle, including CDK1, CHEK1, CDC25C, BUB1, CDC20, and TTK, which not only are related to breast cancer patient survival but also have existing targeted drugs." (PMID 38166892, 2024). "A molecular mechanism has recently been identified in which t-DARPP phosphorylated by CDK-1 and -5 activates PKA kinase function by forming a direct complex with PKA regulatory subunits in breast cancer cells overexpressing t-DARPP32,33." (PMID 36966223, 2023).
breast cancer (continued). "A mixed treatment by means of CDK-1 and PARP-1 inhibitors resulted in radical breast cancer cell growth reduction." (PMID 37762072, 2023). "Recently, several studies have investigated the prognostic value of various genes in breast cancer, including NUSAP1, maternal embryonic leucine zipper kinase (MELK), and CDK1." (PMID 38084295, 2023). "Conversely, its expression promoted breast cancer progression by interacting with E2F transcription factor 1 (E2F1), resulting in CDK1 activation in MDA-MB-231 cells." (PMID 37498296, 2023). "Phosphorylation of EZH2 at T435 and T487 by CDK1 and CDK2 epigenetically silences target genes in breast cancers." (PMID 37803297, 2023). "Compounds acting as CDK-1 and/or PARP-1 inhibitors can induct cell death in breast cancer with a selective synthetic lethality mechanism." (PMID 37762072, 2023). "(±)KU inhibits the proliferation of breast cancer cells through the suppression of CSF1R and its downstream signaling molecules, including AKT, cyclinD1 and CDK1." (PMID 36552555, 2022). "In breast cancer cells, knocking down USP14 reduced the protein expression of CDK1 by increasing the ubiquitination level, thereby arresting the cell cycle in the G2/M phase, and significantly reducing cell proliferation." (PMID 35549778, 2022). "In animal models of breast cancer, up-regulation of RBM7 which induces activity of CDK1 has been shown to increase tumor growth." (PMID 36266723, 2022). "Treatment of breast cancer cells with 5′-fluorouracil has efficiently reduced expressions of KIAA1429 and CDK1." (PMID 36266723, 2022). "Several lung cancer, diffuse large B-cell melanoma, and lymphoma cases have reported CDK1 overexpression, while CDK2 overexpression has been observed in breast cancer, laryngeal squamous cell cancer, colorectal carcinomas, and melanomas." (PMID 34361615, 2021). "Oncomine analysis revealed that CDK1 and CDC20 expression were obviously elevated in most cancers, especially in breast cancer, colorectal cancer, and lung cancer." (PMID 32127012, 2020). "As a result, there were nearly 2.1% (CDC20, CDK1), 1.2% (RRM2), 0.9% (BUB1B), 0.8% (CCNA2), 0.7% (CCNB2) of breast cancer samples included in cBioPortal had genetic changes." (PMID 33083112, 2020). "Four kinases-serine/threonine-protein kinase Nek2 (NEK2), aurora kinase A (AURKA), cyclin-dependent kinase 1 and 2 (CDK1 and CDK2) were the predicted to be activated across breast cancer, colon cancer, LUAD, ovarian cancer, and UCEC." (PMID 32033228, 2020). "Through the comprehensive analysis of the databases, we found that the expression of CDC20, CDK1, and PLK1 are increased in breast cancer." (PMID 32848800, 2020). "In the current study, we obtained 283 overlapping DEGs and six hub genes (RRM2, CDC20, CCNB2, BUB1B, CDK1, and CCNA2) related to the occurrence and development of breast cancer via comprehensive bioinformatics analysis." (PMID 33083112, 2020). "In contrast, the potent cyclin dependent kinase inhibitor p21 which binds to and inhibits the activity of cyclin-CDK2, -CDK1, and -CDK4/6 complexes, was dose-dependently upregulated in both breast cancer cell lines and to a lesser extend in MCF-10A." (PMID 32292575, 2020). "Inhibiting the expression of CDK1 can suppress tumor cells growth and induce apoptosis in TNBC clinical subtype of breast cancer." (PMID 33083112, 2020). "Our study reflects that CDK1, PLK1, and CDC20 are potential therapeutic targets of podophyllotoxin in breast cancer; among them, PLK1 is more worthy of further exploration." (PMID 32848800, 2020). "Our recent study has also confirmed that CDK1-mediated pT345-EZH2 and pT487-EZH2 facilitate EZH2 ubiquitination and subsequent degradation in breast cancer." (PMID 33308321, 2020). "OGT-mediated O-GlcNAcylation of EZH2 attenuates EZH2 ubiquitination in breast cancer cell; PCAF-mediated EZH2-K348 acetylation inhibits CDK1 catalyzing pT345-EZH2 and pT487-EZH2 and increases EZH2 stability in lung cancer." (PMID 33308321, 2020).
breast cancer (continued). "Later, it was verified by qRT-PCR analysis that CDK1, PLK1, and CDC20 were the direct targets of podophyllotoxin in breast cancer cells." (PMID 32848800, 2020). "To test the generality of the synergy, we knocked down CDK1/CDK4/CDK6 in cell lines derived from different cancer types, including A549 (non-small cell lung cancer) and MCF7 (ER+ breast cancer), and treated them with metformin." (PMID 32811807, 2020). "For breast cancer, the differences of CDC25C (P = 0.001), CDK1 (P = 0.000), CHK1 (P = 0.001), CHK2 (P = 0.000), PLK1 (P = 0.000) and Aurora A (P = 0.000) expression between primary cancer with and without metastasis also had statistical differences." (PMID 32393310, 2020). "More to the point, ANCR is necessary for the binding of CDK1 to EZH2, where CDK1 marks EZH2 for ubiquitin-proteasome degradation via Thr-345 and Thr-487 phosphorylation in breast cancer cells." (PMID 31658672, 2019). "We found that specific genes such as CBL, RHOA, EP300, RAC1, CDK1, and CDH1 are involved in the migration and invasion of breast cancer." (PMID 30930932, 2019). "Our results showed that PIP5Kα is necessary for breast cancer cell proliferation, as evidenced by the increases in the cell proliferation markers E2F1, CDK1 and CCND1 and the decrease in the tumour suppressor FOXO3." (PMID 29851245, 2018). "In the MYC-dependent breast cancer, another alternative is to target MYC’s SL partner gene CDK1, as reported in some small interfering RNA (siRNA) experiment." (PMID 29855504, 2018). "To elucidate the molecular mechanisms responsible for CDK1 degradation via the lysosomal pathway, we used MCF7 cells as a model of human breast cancer." (PMID 28855742, 2017). "Cyclin-dependent kinase 1 (CDK1) is the central mammalian regulator of cell proliferation and a promising therapeutic target for breast cancer." (PMID 28855742, 2017). "As in the human breast cancer cell line MDA-MB-231, Western blotting showed that the expression of cyclin A, cyclin B, and cyclin-dependent kinase-1 (CDK1) was suppressed by apigenin treatment." (PMID 29034071, 2017). "Mechanistically, SL4 induced G2/M arrest in breast cancer cells by activating the MAPK/p21 signaling axis, which subsequently regulated the activity of the CDK1/cyclin A2 and CDK1/cyclin B1 complexes." (PMID 27819344, 2016). "Over expressed in breast cancer cells, the WEE1 protein is a nuclear kinase that helps regulate transition from the G2 phase to mitosis by inhibiting the activity of the CDK1 protein, thus increasing DNA repair in cancer cells prior to mitosis." (PMID 26220712, 2015). "We then inhibited CDKs including CDK4/6, CDK2 and CDK1 individually using either RNAi or small molecule inhibitors, and compared sensitivity to CDK inhibition with MYC dependence in breast cancer cells." (PMID 24444383, 2014). "In this study we used an RNAi approach to identify MYC-dependent breast cancer cell lines and then inhibited CDKs including CDK4/6, CDK2 and CDK1 individually by either RNAi or small molecule inhibitors in both MYC-dependent and MYC-independent cells." (PMID 24444383, 2014). "In previous study, the genes (CDK1, CDK2 and CDK4) were dysregulated in breast cancer, ovarian cancer, colon cancer, hepatocellular carcinoma, thyroid carcinoma, and lung cancer." (PMID 24386425, 2013). "The enzymatic activity of the cyclin-dependent kinases 1 and 2 (CDK1 and CDK2) predicts outcome in breast cancer." (PMID 22108518, 2012). "This provides additional evidence that inhibition of CDK1 and CDK2 is the mechanism by which NU2058 and NU6102 kill breast cancer cells." (PMID 20010939, 2010). "In summary, we have validated CDK2 and CDK1 as therapeutic targets in anti-estrogen-sensitive and resistant breast cancer cells by showing G1 and G2/M accumulation after CDK2, CDK1 or combined CDK knockdown, respectively." (PMID 20010939, 2010). "We measured the specific activities of CDK1 and CDK2 in the four breast cancer cell lines after treatment with 100 nM paclitaxel." (PMID 19239702, 2009).
breast cancer (continued). "We then examined the specific activities of CDK1 and CDK2 in these cell lines and in xenograft models of human breast cancer before and after paclitaxel treatment." (PMID 19239702, 2009). "In the present study we measured both the kinase activity and expression level of CDK1 and CDK2 before and after paclitaxel treatment in human breast cancer cell lines and in xenograft models of human breast cancer." (PMID 19239702, 2009). "In the present study the treatmnet of MCF7 cell treated with the CU (200–500 μL) fraction for 24 h and significantly down regulation of the CDK1, CDC25A and PLK1 which is involved in cell cycle, and responsible for cell cycle arrest in tumour cells of breast cancer." (PMID 40081286, 2025). "CDK1 is recruited to phosphorylate DRP1 S616 that promotes mitochondrial fission and fragmentation, thus facilitating stemness characteristics and metastasis of breast cancer cells." (PMID 40882371, 2025). "CDK1 can be considered an optimal CDK target for breast cancer treatment, promoting MYC-driven transcription and tumorigenesis through mediated ubiquitin ligase activation of FBXO28 and predicting poor survival in breast cancer." (PMID 39991589, 2025). "In the analysis of HER2 status, it was found that the expression level of CDK1 in HER2-negative patients was higher than that in HER2-positive patients, suggesting that CDK1 may play a more important role in HER2-negative breast cancer." (PMID 41278293, 2025). "Leveraging bioinformatics tools and experimental validation, the research explores the interactions between C. urens components and key genes, including CDK1, CDC25A, and PLK1, which are crucial for cell cycle regulation and often dysregulated in breast cancer." (PMID 40081286, 2025). "Therefore, recognizing HMMR as a promising therapeutic target, the study validates the overexpression of HMMR in breast cancer and various pan cancers and its correlation with certain proteins such as AURKA, TPX2, and CDK1 through online databases." (PMID 38576486, 2024). "Hence, targeting CDK1 and DTL presents promising avenues for cancer therapy, particularly in breast cancer, emphasizing the need for further research and clinical trials to establish their efficacy." (PMID 39567714, 2024). "CDK-1 and PARP-1 play crucial roles in breast cancer progression." (PMID 37762072, 2023). "Previous investigators have found that cyclin CDK1, CCNB1 and CCNA2 are commonly overexpressed in TNBC and correlated with worse OS in breast cancer, so they could act as novel biomarkers for TNBC treatment." (PMID 37667382, 2023). "In breast cancer cell lines and primary tumours, the ERRB2-mediated increased phosphorylation of Tyr15 of CDK1 leads to the inactivation of BAD and consequently resistance to taxol-induced apoptosis and drive cells to mitotic slippage and prolonged cell cycle arrest." (PMID 37898722, 2023). "The mode of action of eudesmane SLs involves perturbation of MT stability at the levels of both tubulin polymerization and depolymerization, and upregulation of p-Cdk1 (Tyr15) and cyclin B1 in leukemia (CCRF-CEM murine), breast cancer (MCF-7), and hepatoma (HA22T/VGH) cells." (PMID 35651747, 2022). "Furthermore, siRNA-mediated silencing of CDK1 and CDC20 has significantly repressed cell migration and invasion of two breast cancer cell lines." (PMID 36266723, 2022). "In breast cancer cells, the RNA binding protein KIAA1429 has been shown to interact with CDK1." (PMID 36266723, 2022). "In breast cancer, KIAA1429 played its oncogenic role by regulating CDK1." (PMID 35217651, 2022). "Both CDK1 and COL1A1 are often amplified in breast cancer and high CDK1 mRNA expression significantly correlates with poor prognosis in breast cancer, with trend but not significant effects of both genes on survival of TNBC, possibly due to a smaller number of TNBC patients." (PMID 33911160, 2021).